IL6 (interleukin 6)
Diseases named in the same sentence as IL6 in open-access papers (continued):
Sharing a sentence is not in itself a finding about the gene and the disease.
tumor (continued). "Among the factors for which hampering of the differentiation of DCs is known (IL-10, TGF-β1, VEGF, IL-6, M-CSF, and PGE2), only PGE2 was present in such concentrations in the tumor supernatants to show inhibitory effects on the acquisition of DC morphology." (PMID 31100828, 2019). "Several gerokines are capable of modulating all stages of oncogenesis, from tumor initiation and growth to cancer invasion and metastasis, particularly TNF-α and IL-6." (PMID 30682077, 2019). "These stimulate the tumor cells through a paracrine feedback mechanism, such as the production of angiogenesis factors (IGF, VEGF), interleukin 6, and the Wnt signaling pathway for further ligand production." (PMID 30769952, 2019). "A recent study has shown that rosmarinic acid prevents the secretion of VEGF, IL-6, TGF-β, TNF-α, and NF-kB in H22 tumor-bearing mice, proving its potential as an antitumor agent." (PMID 30871059, 2019). "Their results demonstrated that endothelial cell-secreted factors IL-6, IL-8 and EGF induced the activation of the STAT3/Akt/ERK signaling pathways in HNSCC cells in a contact-independent manner, which lead to increased tumor cell survival and migration." (PMID 30927923, 2019). "CAF contribute to shape the immune cells in tumors by secreting proinflammatory cytokines and chemokines, notably TGFβ, IL-6 and CCL2, to recruit immunosuppressive cells into the tumor stroma and reject effector T cells." (PMID 30871158, 2019). "Taken together, these results suggest that IL-6, IL-10, and IL-21 from TTRAP augment the differentiation and immunosuppressive function of TRAPs-induced B cells to facilitate tumor growth and metastasis." (PMID 31300052, 2019). "Several studies indicated that TAMs secrete various kinds of cytokines including growth factor, for example EGF and IL-6, and EGF strongly induces tumor cell proliferation." (PMID 31601953, 2019). "For example, tumor-derived EVs carry pro-angiogenic factors such as IL-6 and VEGF stimulate endothelial cell proliferation and neo-vascularization within the growing tumor, and EV nSMase2 stimulates endothelial cells and angiogenesis." (PMID 30895170, 2019). "The IL-6/JAK pathway is the main responsible of Tyr705 phosphorylation and activation of this pathway contributes to tumor development in many experimental models." (PMID 31143708, 2019). "Inactivating IRIS in vivo also converts TNBC tumors into luminal A tumor cells, blocks MSC recruitment into tumors, and significantly suppresses the secretion of high-level IL-6 and PGE2 into patients’ circulation." (PMID 31014367, 2019). "TAMs-derived IL6 activated the JAK2/STAT3 pathway, and activated STAT3 transcriptionally inhibited the tumor suppressor miR-506-3p in CRC cells." (PMID 30927925, 2019). "Our laboratory previously demonstrated that 2 weeks of systemic IL-6 overexpression is sufficient to induce STAT3 and suppress basal muscle protein synthesis in non-tumor-bearing mice." (PMID 30918582, 2019). "Both in vitro and in vivo studies demonstrated that high local IL-6 levels can stimulate VEGF production and promote tumor angiogenesis, and development of cervical cancer." (PMID 31089160, 2019). "M1 macrophages play critical roles in innate host defense and killing tumor cell by producing reactive oxygen/nitrogen species (ROS/RNS) and pro-inflammatory cytokines such as IL-1β, IL-6, tumor necrosis factor α (TNF-α)." (PMID 31629410, 2019). "IL-6 subsequently led to STAT3 activation and MMP9 expression in tumor cells, enabling increased metastatic invasion." (PMID 31921140, 2019). "Diverse cytokines and factors, including VEGF, granulocyte-macrophage colony stimulating factor (GM-CSF), IL-6, IL-10, TGF-β, interferon (IFN)-γ, IL-1β, and CCL2, are main attractors of MDSCs toward tumor tissue and affect their activation." (PMID 31484464, 2019). "Tumor-secreted CCL2 signals through the CCR2 receptor expressed on TAMs and result in release of IL-6 to promote glioma cell invasiveness." (PMID 31611871, 2019).
tumor (continued). "Specifically, IL-6 was previously shown to be required for HGG development in a mouse model, and to increase tumor cell invasion and angiogenesis." (PMID 31361777, 2019). "Studies have shown that malignant ascites serves as an important tumor microenvironment, which is enriched with tumor-promoting factors such as TGFβ, hepatocyte growth factor (HGF), IL-6, IL-8, IL-10, vascular endothelial growth factor (VEGF) and so on." (PMID 31405096, 2019). "In line with an important role of EGFR and IL6 signaling in GLI-driven cancers, genetic and pharmacological inhibition of EGFR and IL6/JAK2/STAT3 signaling, respectively, interferes with GLI-driven tumor growth." (PMID 30991683, 2019). "HGSOC ascites are a pro-inflammatory tumor environment that contains a variety of cytokines, chemokines and growth factors including leptin, hepatocyte growth factor (HGF), IL-6, and CCL18." (PMID 31039761, 2019). "MDATO/OSM tumor-bearing animals +TET had a 32-fold higher expression of OSM in their tumors compared to –TET tumors and 10.8-fold higher IL-6 expression level, as measured by western blot analysis." (PMID 31007849, 2019). "This is suggested to occur, in part, through the chronic induction of pro-survival cytokines, such as IL-6 and IL-8, in the TME and the selective elimination of tumor clones that retain sensitivity to IFN-dependent genotoxic or cytotoxic stress." (PMID 31842362, 2019). "Our previous study demonstrated that HBV-derived niche IL-6 can upregulate OCT4 expression through insulin-like growth factor 1 receptor (IGF-1R) signaling and the OCT4 expression can result in early tumor recurrence." (PMID 31771617, 2019). "Several cytokines including IL-6, IL-8, IL-10, and VEGF have been found to be secreted at higher levels by MSCs activated by IL-37, macrophages, or tumor cells." (PMID 31130595, 2019). "In cancer cachexia, various tumor and host factors influence skeletal muscle mass homeostasis: e.g., proteolysis-inducing factor (PIF) and cytokines, such as TNF-α, and IL-6." (PMID 30754663, 2019). "RT-PCR analysis and ELISA showed that hTRAPs from cancer patients and tumor cell lines efficiently induced human peripheral blood CD4+ T cells to express IL6 transcript and secrete IL-6." (PMID 31300052, 2019). "To confirm the effect of TAMs on tumor metastasis in vivo, we injected HCT116 alone, HCT116 + TAMs/si-control, or HCT116 + TAMs/si-IL6 into nude mice via the tail vein." (PMID 30927925, 2019). "Some examples of cytokines that are involved in inflammation and the tumor microenvironment include tumor-necrosis factor-α (TNF-α), interleukin-6 (IL-6), transforming growth factor ß (TGF-β), and interleukin-10 (IL-10)." (PMID 30838040, 2019). "In conclusion, pro-inflammatory molecules such as IL-6, IL-8, and TNF-α can lead to Notch signaling activation, enhancing tumor-promoting effects on epithelial cells." (PMID 30917608, 2019). "These inflammatory mediators including interleukin-6 (IL-6), the chemokine IL-8, and tumor necrosis factor (TNF-α) promote the recruitment of immune cell populations to the tumor site." (PMID 31531020, 2019). "In most studies using CAF coculture methods, tumor cells obtained CDDP resistance through CAF-secreted chemokines or growth factors, such as interleukin (IL)-6, IL-8, IL-11, insulin-like growth factor 1, or transforming growth factor-β (TGF-β)." (PMID 31450627, 2019). "Moreover, IL-6 and IL-8 may promote tumor progression in TNBC cells." (PMID 29902993, 2018). "Both IL-6 and CCL2 play a major role in promoting tumorigenesis by altering the primary tumor immune microenvironment and enhancing a more aggressive primary tumor phenotype." (PMID 30458886, 2018). "Concurrent inhibition of IL-6 and CXCL8 expression in TNBC cells inhibits colony formation, cell survival, and tumor growth." (PMID 30034618, 2018).
tumor (continued). "Cytokines, chemokines, and growth factors such as IL-6, IL-8, IL-1β, TNF-α, TGF-β, GM-CSF, VEGF, and angiopoietins have been shown to promote angiogenesis and tumor metastasis." (PMID 29541344, 2018). "In the same way, different proinflammatory cytokines, like IL-6 and TNF-α, are described as tumor promoters and are related to poor prognosis." (PMID 29315242, 2018). "It has been demonstrated recently that IL-6 levels were markedly upregulated in HNSCC patients and high IL-6 expression independently predicts tumor recurrence, metastasis, and poor survival." (PMID 30108590, 2018). "AIRE being a regulator of IL-6 malignancy gene shows lymphadenopathy and inflammation in AIRE+/+ mice and only a small benign tumor is observed AIRE−/− mice." (PMID 29795364, 2018). "In a similar manner, PGE2(+) fibroblasts enhance tumor growth through secretion of IL-6; thus, controlling the ratio of PGE2(+/−) fibroblast subpopulations can either enhance or suppress tumor growth in a breast cancer model." (PMID 29732370, 2018). "The results showed that IL-6, as the effect factor of COX-2, can promote angiogenesis and tumor growth." (PMID 30216977, 2018). "IL-6 activates STAT3 and promote angiogenesis and tumor invasion through VEGF and matrix metalloproteinases expression." (PMID 30167088, 2018). "Primarily, they contribute to the homing of cancer cells and fulfill this role upon their mobilization from the blood by tumor-derived chemoattractants (e.g., CCL2/MCP-1, IL-6, MIF, and CSF-1) and differentiation into TAMs." (PMID 28956065, 2018). "We tested agents targeting the IL-6 and CCR5 pathways in athymic mice with TNBC tumor xenografts to extend these findings." (PMID 29898755, 2018). "In fact, there was a high correlation between leukocyte number, IL-6, haptoglobin, SAA plasma concentration and a number of lung metastases in tumour-bearing mice." (PMID 29788918, 2018). "In relation to the increase in T cells, our results confirmed the induction of genes as Cd3g, Cd4, Il6, Il10 and Il12a in spleens of Ats1-KO mice, independently of the absence or presence of B16F1 tumours." (PMID 30166561, 2018). "Taken together, these findings show that IL-6 and CCL5 signaling, which promote crosstalk between TNBC and lymphatic vessels, are key enhancers of TNBC tumor growth and metastasis." (PMID 29898755, 2018). "Multiple inflammatory cytokines, including IL-1β, IL-6, and TNF-α, increase proliferation and invasion of tumor cells." (PMID 30298062, 2018). "We used multiplex ELISA to demonstrate the presence of IL1B, IL6, IL8, IL10, IL18, TNF and IFNG in the cystic fluid and whole ACP tumour protein lysates." (PMID 29541918, 2018). "IL‐6 plays a vital role in bridging chronic inflammation to HCC progression and is correlated with tumour metastasis." (PMID 29689643, 2018). "Since STAT3 is a well known downstream effector of IL-6 and TNF-alpha, these data further support the ability of trabectedin to inhibit proinflammatory cytokines secretion from senescent tumor cells." (PMID 29731994, 2018). "A fourth proposed mechanism cites the fact that tumor cells can produce CRP themselves, and they are also able to release cytokines such as IL-6 and IL-8, which contribute to the increase in CRP levels." (PMID 29668751, 2018). "GBM plays role in generating immunosuppressive microenvironment by producing different immunosuppressive cytokines including IL-6, IL-10, and TGF-β as well as tumor aggravating IL-1 and basic fibroblast growth factor (bEGF) resulting in neuroinflammation." (PMID 29651429, 2018). "To further confirm the correlation of IL‐6 with PD‐L1, we examined expression levels of IL‐6 and PD‐L1 in human CRPC tumor tissue samples." (PMID 28865178, 2018). "Hyperthermia hase been shown to modify the tumor vasculature by upregulating the adhesion of molecules E/P-selectins and ICAM-1 expression by inducing IL-6 trans-signalling on the endothelium." (PMID 30126117, 2018).
tumor (continued). "TAMs collaborate in angiogenesis through secretion of different substances among which stand out VEGF, epidermal growth factor (EGF), TGF-β, IL6 and matrix metalloproteinases (MMPs) that remodel the ECM in order to facilitate tumor growth." (PMID 30567306, 2018). "Taken together, these results demonstrate that E2 up-regulate IL6 expression by activating ERβ via activation of PI3K/AKT and MAPK/ERK pathways to promote tumor growth in vivo." (PMID 29970138, 2018). "Under conditions of chronic inflammation, such as cancer, MDSCs are released from the bone marrow and undergo continuous expansion in response to tumor secreted-growth factors such as MCSF, VEGF, TNF-α, and IL-6." (PMID 29805773, 2018). "HRG overexpression was shown to increase IL6 and IL12 production in macrophages as compared to HRGlow tumours." (PMID 30577495, 2018). "The serum levels of both IL-6 and TNF-α level was found to be substantially higher in untreated tumor bearing mice whereas both CSL and bortezomib treated group had decreased levels of IL-6 and TNF-α as compared to control group." (PMID 29773987, 2018). "NF-κB signaling in cancer cells can be activated by factors such as IL-1β, TNFα and IL-8, IL-6 and MCP-1 secreted by cells in the microenvironment of the tumor, e.g. macrophages or adipocytes." (PMID 29930291, 2018). "Some cytokines and chemokines secreted by these populations (and other cells in the microenvironment) that can promote tumor growth include TNF-α, IL-6, IL-8 and IL-17." (PMID 30613350, 2018). "Our previous studies indicated that the MK2 pathway regulates IL-1β, IL-6, and TNF-α in CRC tumor models." (PMID 30298062, 2018). "For instance, HSP70+ lung tumor-derived exosomes induce activation of NF-kB and secretion of IL-6, IL-8, and MCP1 by MSCs, in a TLR2-mediated signaling, leading MSCs into a more inflammatory and tumor supportive phenotype." (PMID 29515996, 2018). "In turn, growth promoting factors including IL6, CCL2, VEGF, and CXCL2 are released from the osteoblasts, which promote tumor cell growth, again initiating an additional cycle." (PMID 29642534, 2018). "The end targets of these pathways, including cytokines (IL1A/B, IL6, IL8, IL18) and genes related to cell proliferation (JUN, SRF), were upregulated, suggesting that the activation of these TLRs leads to tumor growth." (PMID 29912993, 2018). "The combined inhibition of both VEGF and IL-6 was proposed to have a promising antitumor effect, and knockdown of both IL-6 and VEGF in a mouse model inhibited tumor development and cell infiltration." (PMID 30283098, 2018). "Some studies have shown elevated serum and cancer tissue IL-6 levels in CRC patients, and its concentration is correlated with tumor size, metastasis, and reduced survival." (PMID 30154846, 2018). "Consistent with our mouse tumor model with reduced IGF-1R signaling, low IGF-1R is inversely correlated with IL-6, CCL2, and MMP9 expression in human tumors." (PMID 30458886, 2018). "These factors include cytokines (such as interleukin-6 (IL-6)), TGF-β, and lipid factors, which mediate the inflammatory, proliferative, and proangiogenic activities of platelets to promote tumor growth, tissue invasion, and metastasis." (PMID 29987226, 2018). "Here, we present more evidence that both IL-6 and CCL5 are key factors in TNBC lymphangiogenesis, tumor growth, and thoracic metastasis." (PMID 29898755, 2018). "Mice with tumors had elevated levels of inflammatory cytokines including IL-1α, IL-6, MIP-1α and G-CSF and lower levels of TNFα and CXCL1 compared to non-tumor bearing mice (all p < 0.05; statistics are provided in S1 Table)." (PMID 30532184, 2018). "This group argues that the effect of TBK1/IKKε is at the level of T cells, where IL-2 and IFNγ are increased with inhibition, and at the tumor cell level where TBK1/IKKε inhibition leads to decreased C-C motif chemokine ligand 5 (CCL5) and IL-6." (PMID 30223576, 2018).
tumor (continued). "In this paper we developed an experimentally based mathematical model for the growth dynamics of HNSCC tumor xenografts, which were generated by transplanting a small number of primary human cancer stem cells (ALDHHIGHCD44HIGH) in IL-6+/+ immunodeficient mice." (PMID 29351275, 2018). "Some tumor samples contained moderate levels of reads mapping to ORFK2, the viral interleukin-6 (vIL-6) homolog, or ORFK5, the ubiquitin ligase modulator of immune response (MIR2)." (PMID 30557332, 2018). "Next to STAT3, NF-κB is known to regulate the expression of many tumor-promoting genes, including VEGF, IL-6, TNF-α, and cyclooxygenase 2 (COX2), which support its crucial role in the activation of TAM2 in the TME." (PMID 30233579, 2018). "Tumor cell overexpression of S1P3 mimics this pathway, enhancing IL-6 and CCL-2 production and elevating BTB permeability." (PMID 30006619, 2018). "Specifically, chemerin contributed to tumor growth by inducing phosphorylation of p38 and ERK 1/2 MAPKs and upregulating IL-6, MMP-7, and VEGF." (PMID 30555465, 2018). "We also show that the suppression of SOCS3, including the blockade of IL-6 signaling, can induce TRAIL sensitivity, thus leading to the inhibition of tumor growth in IFN-α-resistant RCC cells." (PMID 30167088, 2018). "Adipocyte-derived factors, such as leptin, interleukin-6 (IL-6), adiponectin, tumor necrosis factor (TNF-α), monocyte chemotactic protein-1 (MCP-1) and endotrophin (ETP), function within the tumor microenvironment to promote tumor progression." (PMID 30563531, 2018). "This study provides evidence that markers of tumour biology, specifically vasculature immaturity (% IMM) and tumour epithelial 8-oxo-dG in the tissue and serum IL6 and IL8 stratify survival outcome of mCRC patients on bevacizumab treatment." (PMID 29535825, 2018). "The hypoxic tumor microenvironment causes selective up-regulation of PD-L1 on splenic MDSCs and PD-L1 blockade could enhance MDSC-mediated T-cell activation, accompanied by the concomitant down-regulation of immuno-suppressive cytokines IL-6 and IL-10 secreted by MDSCs." (PMID 30619850, 2018). "Using specific inhibitors, we demonstrated that each of these cytokines, particularly IL‐6 and GRO‐α, modulates the invasive behaviour of tumour cells, whereas the mechanism of transendothelial migration is completely independent of GRO‐α/CXCR2 signalling." (PMID 29517849, 2018). "The presence of cytokines in the ACP tumours was also assessed by multiplex ELISA against IL1B, IL6, IL8 (CXCL8), IL10, IL18, TNF (TNFα) and IFNG (IFNγ), which revealed the expression of all of these but IFNG in protein lysates from eight human ACPs." (PMID 29541918, 2018). "In our earlier work we elucidated the role of IL-6 in TNBC growth and metastasis by depleting its levels in the TCM administered to the animals prior to tumor inoculation." (PMID 29898755, 2018). "Proliferating tumor cells can secrete prostaglandins, PTH, activated vitamin D, IL-6 and tumor necrosis factor (TNF), leading to an increase in RANKL expression on OBs and BM stromal cells, which stimulates OC numbers, survival and activity." (PMID 29461491, 2018). "IL-6/STAT3 signaling recruits and modulates function of tumor-infiltrating myeloid cell populations in cancer patients." (PMID 29541413, 2018). "Similar findings were observed after inhibition of the IL-6/STAT3 pathways, leading to a significant inhibition of MDSC expansion and tumor growth of the murine TC1 tumor model." (PMID 30349530, 2018). "Other papers proved that systemic IL-17, through activation of the IL-6/Stat3 pathway and release of MMP2/9, TNF-α, and vascular endothelial factor (VEGF), induces tumor cell migration and metastatic growth in lung cancer-bearing mice." (PMID 30200242, 2018). "Tumor cells, which reach the bone microenvironment, secrete factors, such as PTHrP, which stimulate the osteoblasts to secrete RANKL, IL-8, IL-6, and IL-1." (PMID 29416737, 2018).